TRIP11 (thyroid hormone receptor interactor 11)
Description:
Is a membrane tether required for vesicle tethering to Golgi. Has an essential role in the maintenance of Golgi structure and function. It is required for efficient anterograde and retrograde trafficking in the early secretory pathway, functioning at both the ER-to-Golgi intermediate compartment (ERGIC) and Golgi complex. Binds the ligand binding domain of the thyroid receptor (THRB) in the presence of triiodothyronine and enhances THRB-modulated transcription.
Synonyms: TRIP-11; GMAP-210; CEV14; Trip230; GMAP210; ACG1A; ODCD; ODCD1
Tractability: Antibody: UniProt places it where antibodies can reach, with high confidence. PROTAC: ubiquitination databases record sites on it; its protein half-life has been measured.
Gene: Protein-coding gene on chromosome 14 (91,965,991 to 92,040,896, reverse strand). Ensembl gene ENSG00000100815.
Subcellular location: Golgi apparatus, cis-Golgi network membrane; Cytoplasm, cytoskeleton; Endoplasmic reticulum-Golgi intermediate compartment membrane
Subcellular location (Human Protein Atlas): Golgi apparatus; Primary cilium
Pathways (Reactome):
Disease: Signaling by FLT3 fusion proteins
Organelle biogenesis and maintenance: Intraflagellar transport
Vesicle-mediated transport: Intra-Golgi traffic
Gene Ontology:
Molecular function: protein binding; small GTPase binding; transcription coactivator activity
Biological process: cartilage development; Golgi ribbon formation; endoplasmic reticulum to Golgi vesicle-mediated transport; Golgi organization; transcription by RNA polymerase II; positive regulation of DNA-templated transcription; protein localization to ciliary membrane
Cellular component: endoplasmic reticulum-Golgi intermediate compartment; endoplasmic reticulum-Golgi intermediate compartment membrane; Golgi apparatus; Golgi membrane; transport vesicle; acrosomal membrane; cis-Golgi network; cytoskeleton
Genetic constraint (gnomAD): Loss-of-function variants: 138 observed, 217.3 expected, observed/expected ratio (o/e) 0.64, 90% interval 0.55 to 0.73. The upper end of that interval is the gene's LOEUF score, 0.73, which puts it in group 2 of 6, group 1 being the genes least tolerant of losing a copy. Missense variants: 2,015 observed, 2,280.3 expected, observed/expected ratio (o/e) 0.88, 90% interval 0.85 to 0.92. Synonymous variants: 753 observed, 806.73 expected, observed/expected ratio (o/e) 0.93, 90% interval 0.88 to 0.99.
Gene-disease validity (ClinGen):
ClinGen rates the evidence that TRIP11 causes each of these diseases.
TRIP11-related skeletal dysplasia (autosomal recessive): Definitive. Any skeletal dysplasia in which the cause of the disease is a variation in the TRIP11 gene.
Homologues: Orthologues: chimpanzee TRIP11 (99% identical), macaque TRIP11 (89% identical), pig TRIP11 (88% identical), dog TRIP11 (87% identical), guinea pig TRIP11 (83% identical), mouse Trip11 (83% identical), rabbit TRIP11 (81% identical), rat Trip11 (79% identical), tropical clawed frog trip11 (59% identical), zebrafish trip11 (53% identical), Caenorhabditis elegans sql-1 (16% identical), Drosophila melanogaster Gmap (15% identical).
Diseases named in the same sentence as TRIP11 in open-access papers:
TRIP11 is named in the same sentence as 38 diseases in open-access papers, as found by Europe PMC text mining. Sharing a sentence is not in itself a finding about the gene and the disease. The quoted sentences say what the papers report.
Achondrogenesis type 1A (7 papers, 2012 to 2025). Achondrogenesis type 1A (ACG1A), a form of achondrogenesis (see this term), is a very rare, lethal skeletal dysplasia characterized by dwarfism with extremely short limbs, narrow chest, short ribs that are easily fractured, soft skull bones and distinctive histological features of the cartilage. "In humans, severe and hypomorphic mutations in the Trip11 gene encoding GMAP210 cause achondrogenesis type 1A (ACG1A) and odontochondrodysplasia (OCDC), respectively." (PMID 40824304, 2025). "In contrast, the fetus was found homozygous for the TRIP11 mutation, and achondrogenesis type IA diagnosis was, thus, molecularly confirmed, indicating two different skeletal dysplasia forms in the family." (PMID 34149817, 2021). "PCT showed a TRIP11 variant in both parents, associated with achondrogenesis type 1a, matching the phenotype." (PMID 33742171, 2021). "Inactivating mutations in the ubiquitously expressed membrane trafficking component GMAP-210 (encoded by Trip11) cause achondrogenesis type 1A (ACG1A)." (PMID 29180569, 2018). "Based on suspicion of odontochondrodysplasia in the index patient and of achondrogenesis type 1A in the fetus, TRIP11 was an obvious candidate gene." (PMID 34149817, 2021).
odontochondrodysplasia (7 papers, 2019 to 2025). "Specifically, hypomorphic TRIP11 mutations impaired secretion from the Golgi apparatus in patients suffering from odontochondrodysplasia." (PMID 36799927, 2023). "Mutations in the TRIP11 gene encoding GMAP210 are causative of the human skeletal diseases achondrogenesis type 1A and odontochondrodysplasia." (PMID 40824304, 2025). "For example, mutation of the golgin GMAP210 (TRIP11) gives rise to two skeletal disorders in humans, namely achondrogenesis 1A (ACG1A) and odontochondrodysplasia (ODCD), which are both associated with defective trafficking and glycosylation of matrix proteins." (PMID 35023559, 2022). "Here, we describe an 11-year-old Finnish girl, born to unrelated healthy parents, who had severe short stature and a phenotype similar to odontochondrodysplasia (ODCD), a monogenic skeletal dysplasia caused by biallelic TRIP11 variants." (PMID 34149817, 2021).
chondrodysplasia (1 paper, 2018). "Recessive loss-of-function mutations in the lamin B receptor (LBR) and the thyroid hormone receptor interactor 11 (TRIP11) genes cause lethal human chondrodysplasias with distinct phenotypes." (PMID 30518689, 2018).
hearing loss (1 paper, 2025). "Although the majority of cases were associated with biallelic variants in TRIP11, one study described a homozygous truncating variant in MIA3, encoding TANGO1, in four sibs with ODCD in association with insulin-dependent diabetes, hearing loss, obesity, and intellectual disability." (PMID 40119123, 2025).
Infertility (1 paper, 2022). "In addition, TRIP11 male germ cell-specific conditional knockout mice exhibit infertility." (PMID 36459505, 2022).
osteochondrodysplasia (1 paper, 2018). A term referring to disorders characterized by abnormalities in the development of bones and cartilage. "Similarly, autosomal dominant mutations in COL2A1 are responsible for a number of osteochondrodysplasias, and mutations in both COL2A1 and TRIP11 are implicated in Type 2 and Type 1A achondrogenesis, respectively." (PMID 29567674, 2018).
pineal dysgerminoma (1 paper, 2025). "In addition to the EOCRC initially reported at the age of 37, patient EOCRC#64 (TRIP11 variant) was diagnosed with pineal dysgerminoma at the age of 21 and relapsed with a malignant germinoma." (PMID 40429818, 2025).
renal cell cancer (1 paper, 2019). "The pathway involving TRIP11 and triiodothyronine is necessary for localization of TRIP11 to the nucleus and was found to be disrupted in renal cell cancer, leading to progression." (PMID 30962767, 2019).
skeletal dysplasia (12 papers, 2015 to 2025). Any Mendelian diseases that affects growth and development of the skeleton. "Since the patient only harbored a heterozygous TRIP11 mutation, we searched for other potential gene variants contributing to her skeletal dysplasia." (PMID 34149817, 2021). "Additionally, in one skeletal dysplasia case, only a maternally inherited variant was highlighted in the TRIP11 gene, causative of autosomal recessive Achondrogenesis, type IA (MIM: # 200600)." (PMID 41153384, 2025). "Mutations in TRIP11 have been associated with lethal skeletal dysplasia." (PMID 36799927, 2023). "For instance, a nonsense mutation in the gene coding for GMAP-210 (also known as TRIP11) causes neonatal lethal skeletal dysplasia in both mice and humans." (PMID 32629928, 2020).
cancer (5 papers, 2014 to 2025). A tumor composed of atypical neoplastic, often pleomorphic cells that invade other tissues. "Of the other 16 genes, COL5A1, GABBR1, HACE1, EPHA7, and TRIP11 have well-documented associations with cancer." (PMID 30962767, 2019). "Interestingly, in addition to PDGFRA we found four genes previously shown to be driver mutations in different cancers: SETD2, FAT4, TRIP11 and PPP3CA (highlighted genes)." (PMID 32603362, 2020).
TRIP11 also shares sentences with these, for which no sentence is quoted: achondrogenesis (3 papers); breast carcinoma (2); Tetralogy of Fallot (2); tumor (2); achondrogenesis type IA (1); acute promyelocytic leukemia (1); ciliopathy (1); cystic kidney disease (1); dysplasia (1); eosinophilia (1); frontometaphyseal dysplasia (1); hydrocephaly (1); insulin-dependent diabetes (1); Intellectual disability (1); Kidney Cyst (1); male infertility (1); Meckel syndrome type 13 (1); Meckel syndrome, type 2 (1); myeloid neoplasm (1); Obesity (1); omphalocele (1); osteofibrous dysplasia (1); polydactyly (1); prostate carcinoma (1); pulmonary diseases (1); respiratory distress syndrome (1); skeletal diseases (1); spondylometaphyseal dysplasia (1).